BDNF (brain derived neurotrophic factor)
Diseases named in the same sentence as BDNF in open-access papers (continued):
Sharing a sentence is not in itself a finding about the gene and the disease.
depression (continued). "Serum interleukin‐6 (IL‐6), irisin, brain‐derived neurotrophic factor (BDNF), kynurenine, and cathepsin B were analyzed and compared to surrogates of depression and quality of life." (PMID 33655551, 2021). "Intriguingly, BDNF levels in several brain regions are remarkably reduced in depression-like animals and depressed patients." (PMID 33967844, 2021). "The PI3K/Akt signaling pathway is the primary downstream signaling pathway in BDNF/TrkB signaling, regulating neuronal cell growth and survival in the hippocampus and mediating stress-induced depression and antidepressant effects." (PMID 33584387, 2021). "In an electroconvulsive therapy (ECT) study in treating depression, the BDNF level was increased in the hippocampus." (PMID 34007290, 2021). "They found that BDNF and the expression of TrKB were significantly reduced in BD compared to unipolar depression." (PMID 34645783, 2021). "Specifically, BDNF mRNA levels are reportedly low in animal studies of depression or stress, while this reduction is ameliorated in animals administered antidepressants." (PMID 34439529, 2021). "Rodents were exposed to chronic stress, early life stress or unpredictable stress have significantly reduced BDNF expression in the hippocampus, resulting in impairment of synaptic plasticity and depression-like behaviors." (PMID 32203159, 2021). "The role of CREB-BDNF in depression is via tyrosine receptor kinase B (TrkB), a member of the tyrosine kinase family, that can specifically bind to BDNF with a high affinity." (PMID 34358084, 2021). "Numerous studies report alterations in BDNF levels in human serum in various neurological conditions, including mood disorders such as depression." (PMID 33462179, 2021). "CSS alleviated anxiety and depression by inducing NF-κB-involved BDNF expression through the regulation of gut inflammation and microbiota." (PMID 34391441, 2021). "Based on the molecular mechanism underlying the action of rapid-antidepressant, our research focuses on the regulation of BDNF expression in depression, and firstly discover a siRNA drug for depression treatment." (PMID 34772918, 2021). "It has been found that the DNA methylation level of BDNF in the depression group exceeded that in the bipolar disorder and healthy groups." (PMID 34299040, 2021). "Excessive inflammatory cytokines can influence other mechanisms of depression by decreasing the production of serotonin and BDNF, fueling glutamate excitotoxicity and disrupting the HPA axis and hormone balance." (PMID 33669121, 2021). "There is a growing interest in the role of brain-derived neurotrophic factor (BDNF) in major depressive disorder (MDD)." (PMID 34325733, 2021). "In recent years, new mechanisms of action have been discovered for long-standing antidepressants that also shed new light on depression, including the sphingolipid system and the receptor for brain-derived neurotrophic factor (BDNF)." (PMID 34577594, 2021). "First, we aim to evaluate the allostatic load of soldiers diagnosed as suffering from PTSD, anxiety, or depression based on nocturnal urinary cortisol, morning blood cortisol, 8-iso-PGF2α excretion, and BDNF concentrations." (PMID 34698145, 2021). "Summarizing these findings, we observed that RT induces an increase in BDNF, antioxidant capacity, and quality of life, induced a change in depression symptoms in patients with CKD under hemodialysis treatment." (PMID 34769814, 2021). "Meta-analyses have shown that BDNF concentrations are lower in patients with depression than in healthy controls and that levels increase with successful antidepressant treatment." (PMID 33436036, 2021). "Depression is often accompanied by a decrease in the relative content of BDNF and monoamine neurotransmitters." (PMID 33954123, 2021). "Structural changes in neuroplasticity, altered intrinsic signaling, i.e., of serotonin and BDNF, and impaired neurogenesis are observed in stress-related events, Alzheimer’s disease (AD), or major depression." (PMID 34109176, 2021).
depression (continued). "The healthy controls had significantly higher serum BDNF concentration than patients with depression (F = 5.859, p = 0.017)." (PMID 34362162, 2021). "Treating treatment-resistant depression is an increasing problem; hence, this review includes the C category study of plasma BDNF levels before and after ketamine infusions." (PMID 34362162, 2021). "Cortisol, BDNF, and cytokines dynamics have also been studied in depression, fatigue, and other psychological disorders, as they often coexist with anxiety; however, results from these studies are inconsistent and inconclusive." (PMID 34213086, 2021). "This is the first study to interrogate the relationship between maternal and fetal serum BDNF at term in the context of maternal symptoms of depression and anxiety." (PMID 33462179, 2021). "While impaired hippocampal neurogenesis can lead to depression, BDNF upregulation stimulates hippocampal neurogenesis, followed by an induced antidepressant effect." (PMID 34577589, 2021). "Emerging evidence suggests that the hypothalamic–pituitary–adrenal (HPA) axis, neurotransmitters, intestinal flora, and brain-derived neurotrophic factor (BDNF) are involved in the pathology of depression." (PMID 34475963, 2021). "A plausible explanation for this effect was that chronic BDNF induced a concomitant enhancement of [Ca2+]i fluctuations in some neurons and depression in others." (PMID 33500423, 2021). "Candidate genes that undergo DNA methylation, such as brain-derived neurotrophic factor (BDNF), NR3C1 (encoding the glucocorticoid receptor), SLC6A4 (encoding the serotonin transporter), have been regarded as potential biomarkers of depression." (PMID 33815064, 2021). "It has been found in patients with depression that the use of antidepressants can increase the concentration of BDNF in the blood." (PMID 34299040, 2021). "Here, we show that the leptin receptor (LepRb) colocalizes with brain-derived neurotrophic factor (BDNF), a key player in the pathophysiology of major depression and the action of antidepressants, in the dentate gyrus of the hippocampus." (PMID 33106599, 2021). "BDNF has been reported to play an important role in depression pathogenesis in a region-specific manner." (PMID 34577589, 2021). "Regarding potential biomarkers, brain-derived neurotrophic factor was suggested to differentiate bipolar from unipolar depression and a possible cut-off value was proposed." (PMID 33946871, 2021). "Although there is a link between inflammation and BDNF, it has been reported that BDNF plays a role in sleep deprivation and depression." (PMID 33915758, 2021). "BDNF levels in bipolar disorder patients were significantly lower than that of the normal control group, which included a healthy control group and a unipolar depression group." (PMID 35194435, 2021). "Lower levels of BDNF in adolescents with depression compared to controls was found, with a gender bias with greater reduction in females." (PMID 34575175, 2021). "BDNF is a key NF that regulates cell survival, substantially contributes to adult neurogenesis, and is important for the pathogenesis and treatment of depression." (PMID 34658847, 2021). "Decreased BDNF levels and increased BDNF methylation status, especially in the promoter regions of exons I and IV, were identified in patients with depression." (PMID 33926511, 2021). "Several studies have reported that higher levels of DNA methylation in the BDNF gene are related to bipolar disorder, schizophrenia, borderline personality disorder, and depression." (PMID 34912196, 2021). "Numerous pre-clinical studies have connected stress and an excess of corticosteroids with reduced BDNF signaling in depression-related brain areas." (PMID 34924969, 2021). "In fact, while the mature form promotes long-term potentiation, pro-BDNF facilitates long-term depression." (PMID 33467406, 2021).
depression (continued). "Differential methylation of exon IX of BDNF (both hyper- and hypomethylation) has been found in sufferers of major depressive disorder in addition to reduced expression of BDNF." (PMID 34836233, 2021). "Low levels of hippocampal BDNF are noted in animal models of stress-related depression, and hippocampal BDNF mRNA and protein levels also increase after treatment with classical antidepressants." (PMID 34360959, 2021). "The present study supports the notion that IDO1 antagonizes BDNF effects at the behavioral level in depression." (PMID 33591947, 2021). "Next, further search for drugs acting on the BDNF-mTORC1 pathway or allosteric modulators of mTORC1 is of great significance to improve its role in the pathology of depression, which will greatly improve the situation of female patients." (PMID 33628219, 2021). "Among the regulated genes in neuronal cell lines were synapsin, synaptophysin, Crh, BDNF, and the serotonin 1A receptor, which are highly relevant for depression and antidepressant response." (PMID 34972135, 2021). "In patients with depression, lower serum BDNF concentrations correlated with the severity of depression." (PMID 34300001, 2021). "On the other hand, in other studies, the antidepressant effects of escitalopram were unrelated to the regulation of hippocampal BDNF expression and serum BDNF levels among rats with depression." (PMID 34512130, 2021). "Significant correlation between rs25531 in 5-HTT (P = 0.002) with higher depression scale and rs6265 in BDNF (P = 0.002) and higher stress scale detected in all recruited samples." (PMID 34492034, 2021). "In brief, the current study revealed that Rb1 prevents depression-like symptoms in socially defeated mice, which seems to be facilitated via activation of the hippocampal BDNF–TrkB signaling pathway." (PMID 34658847, 2021). "The oral administration of luteolin (10 mg/kg) also significantly changed the levels of the mature BDNF, the noradrenaline and the dopamine in the hypothalamus of LPS-induced depression mice, and it didn’t significantly affect the level of pro-BDNF." (PMID 34790666, 2021). "The decreased level of hippocampal BDNF in a rat model of depression was found to inhibit neuronal proliferation." (PMID 35155523, 2021). "The dysfunction or damage of the neurotransmission system in the brain, especially involving 5-HT and BDNF, is intensively related to the neurobiological mechanisms of depression." (PMID 35010973, 2021). "Quercetin alleviates LPS-induced depression-like behavior and learning and memory impairment in rats by regulating BDNF-related imbalance of Copine 6 and TREM1/2 expression in the hippocampus." (PMID 34257681, 2021). "Similar to in depression, patients with AN show low levels of BDNF, which generally resolves following weight restoration." (PMID 34836413, 2021). "The link between the gut microbiota and depression is confirmed by the fact that it is involved in the synthesis of serotonin, BDNF and tryptophan metabolism." (PMID 34679364, 2021). "Signaling via BDNF and its receptor, tropomycin receptor kinase B (TrkB), plays a key role in the pathophysiology of depression and in the therapeutic mechanisms of antidepressants." (PMID 34362162, 2021). "Hyperactivation of the immune response also impairs survival and differentiation of progenitor cells, which, together with impaired serotonin and BDNF signaling, are characteristics of major depression." (PMID 34109176, 2021). "In a rodent study, the result found higher BDNF promoter IV methylation levels in the hippocampus of post-stroke depression." (PMID 33815064, 2021). "In recent years, there are enough studies to prove the key role of antidepressant treatment in curing depression through regulation of brain BDNF and via activation of TrkB receptors." (PMID 34944471, 2021).
depression (continued). "External signals mainly regulated the expression of BDNF through the cAMP/PKA–CREB–BDNF pathway, further regulating the growth and survival of cells, and influenced the occurrence and development of depression." (PMID 34220431, 2021). "BDNF production was altered by stress via histone acetylation, which then induced depression-like behaviors in mice." (PMID 34577589, 2021). "According to recent studies, the BDNF signaling cascade is crucial for depression treatment and pathophysiology." (PMID 34658847, 2021). "An animal model of depression presented reduced level of BDNF, and when administrated BDNF seems to display antidepressant effect." (PMID 33530512, 2021). "The BDNF protein along with mRNA in the hippocampus of mice with depression was significantly reduced by learned helplessness." (PMID 34630092, 2021). "The neurobiology of KLK8 is thus functionally related to that of established biomarkers of depression, like Brain-Derived Neurotrophic Factor (BDNF) and Vascular Endothelial Growth Factor (VEGF)." (PMID 34715912, 2021). "There is evidence that BDNF administration into the hippocampus produced an antidepressant effect in the standard behavioral models of depression—the learned helplessness and forced swim paradigms in rats." (PMID 34769417, 2021). "Alterations in BDNF promoter gene methylation are also observed in schizophrenia, depression, bipolar disorder, as well as in the brain tissue of suicide victims." (PMID 34640441, 2021). "Enriched environment during the early development period is effective in alleviating depression induced by ELS through increasing BDNF expression in the hippocampus." (PMID 34890365, 2021). "Studies on BDNF in other psychiatric conditions including major depressive disorder and anxiety in general, and obsessive-compulsive disorder in particular, have similarly reported decreased BDNF levels." (PMID 33572701, 2021). "MiR‐199a‐5p can target WNT2 to enhance the developments of depression by regulating the CREB/BDNF signaling." (PMID 34333859, 2021). "It was shown that BDNF is involved in the regulation of different kinds of behavior, such as exploratory activity, anxiety, aggression and depression-like behavior; however, the precise mechanisms of BDNF action are not fully understood." (PMID 34769417, 2021). "By chronic VCD injection, depression-like behaviors and BDNF expression in the prefrontal cortex and hippocampus were decreased." (PMID 34698102, 2021). "While several studies have shown BDNF decreases in major depressive disorder or psychological stress states, some studies have demonstrated plasma or serum BDNF increases in patients with AD." (PMID 34944580, 2021). "Yueju pill exerted antidepressant effects by regulating PKA/CREB, NMDA, and Akt/mTOR signaling, while Chaihu Shugan San has been suggested to treat depression through BDNF signaling, gut microbiota, and other mechanisms." (PMID 34976096, 2021). "More importantly, the effects of the SSRI were reversed by K252a, anantagonist of TrkB, which suggested that BDNF/TrkB signaling was also involved in theunderlying mechanism of depression- and anxiety-like behaviors in mice." (PMID 34819201, 2021). "Down-regulation of BDNF levels in the hippocampus plays an important role in depression-related symptoms, including cognitive impairment." (PMID 33441611, 2021). "miR‐199a‐5p can target WNT2 to enhance the developments of depressions through the regulations of CREB/BDNF signaling." (PMID 34333859, 2021). "Expression of the microglial marker IBA-1 and inflammatory cytokines (IL1β, TNFα, BDNF) are up-regulated in the brain of patients with major depression and in animal models of depressive-like behavior." (PMID 34236532, 2021). "The imbalance of the pro- and mature forms of BDNF has been observed in depressed patients and in rodent models of depression." (PMID 34298958, 2021).
depression (continued). "Accordingly, we herein aim to systematically evaluate d-serine's role on depression behaviors mediated by BDNF system and in LTD in NAc." (PMID 34654365, 2021). "The function of BDNF in depression pathogenesis is heterogeneous, depending on the brain region and individual circuits." (PMID 34577589, 2021). "Depression is also connected to a decrease in neurotrophic factors, such as brain-derived neurotrophic factor (BDNF)." (PMID 34577630, 2021). "Several studies on stressed rodents and on patients with depression detected decreased levels of BDNF, together with abnormalities in the levels of neurotransmitters and neuroendocrine dysfunction." (PMID 34055858, 2021). "BDNF at intracerebral administration produces long-lasting antidepressant-like effects in experimental models of depression." (PMID 33578683, 2021). "MiR-133b augmentation was associated with decreased apoptosis, repressed inflammatory reaction, and increased expression of GFAP, BDNF and neurotransmitters in hippocampal tissues of depression rats." (PMID 34829888, 2021). "NI is used to characterize the relative contribution of neuroplasticity indicated by the BDNF level to depression symptoms indicated by the score of HAMD-24." (PMID 34776888, 2021). "Our results suggested that mTBI-J treatment has long-term regulation effects on hippocampal BDNF expression, leading to increased depression-like behavior in adulthood." (PMID 34959450, 2021). "In short, BDNF system and synaptic plasticity in NAc are closely related to depression, and d-serine affects BDNF system's function and synaptic plasticity in NAc." (PMID 34654365, 2021). "In both depression and dementia, we observe a disturbance in the brain-derived neurotrophic factor (BDNF) signal pathway." (PMID 34573069, 2021). "Inflammation and trophic factors (brain-derived neurotrophic factor [BDNF], vascular endothelial growth factor, glial cell line-derived neurotrophic factor, and insulin-like growth factor-1) are associated with depression in the general population." (PMID 33104946, 2021). "In the present study, we probed the role of genetic and epigenetic regulation of BDNF in major depression, by focusing on anhedonia, reward learning and cognitive performance as the main outcomes." (PMID 34325733, 2021). "The involvement of BDNF in depression is based on its function as well as evidence from clinical studies." (PMID 34063646, 2021). "In terms of depression, the serum level of BDNF was found to decrease in antidepressant-naive patients, whereas treatment with antidepressants was found to reverse this decrease." (PMID 34063646, 2021). "Our results support the idea of the mechanism of the antidepressant effect, and we discover that there is a direct way for manipulating BDNF expression at post-transcriptional level in depression." (PMID 32203159, 2021). "We found that HEC ameliorated depression symptoms in rats and these effects were probably due to an increase in BDNF proteins and its receptor, TrkB, gene expressions in the prefrontal cortex." (PMID 34046326, 2021). "Several clinical and preclinical reports point to an impairment in neurotrophic factors, mainly BDNF, as the causal role of the atrophy observed in brain areas as PFC or hippocampus in patients diagnosed with major depression." (PMID 34445375, 2021). "A recent study also reported that LIPUS alleviated depression‐like behavior in rats subjected to 48‐h restraint stress while upregulating expression of brain‐derived neurotrophic factor (BDNF) in the hippocampus." (PMID 33112507, 2021). "Some studies have demonstrated that serum BDNF levels are tightly correlated with the course of depression." (PMID 33926511, 2021). "These pieces of empirical evidence seem to support the perspective that decreased BDNF concentrations play a crucial role in the pathophysiology of depression." (PMID 34141514, 2021).